GZMB (granzyme B)
Diseases named in the same sentence as GZMB in open-access papers (continued):
Sharing a sentence is not in itself a finding about the gene and the disease.
ulcerative colitis (2 papers, 2024 to 2025). An inflammatory bowel disease involving the mucosal surface of the large intestine and rectum. "Third, only a limited set of immune markers (CD4, CD8, and IL-6) was analyzed; inclusion of additional cytokines and functional markers (e.g.,TNF-α, TGF-β, FOXP3, IL-17, granzyme B) could provide a more comprehensive understanding of immune regulation in ulcerative colitis." (PMID 41465205, 2025).
abortion (1 paper, 2021). the ending of pregnancy by removing a fetus or embryo before it can survive outside the uterus. "Together, our results indicated that even without the increased expression of GZMB and perforin, γδ T cells in RSA patients might still have elevated cytotoxicity by increasing their CD107a expression and contribute to the recurrent spontaneous abortion." (PMID 34484234, 2021).
Achalasia (1 paper, 2023). A disorder of esophageal motility characterized by the inability of the lower esophageal sphincter to relax during swallowing and by inadequate or lacking peristalsis in the lower half of the body of the esophagus. "We also found many pro-inflammatory factors in expanded effector T cells and effector memory T cells that were more highly expressed in achalasia than in controls, including TNF, IFNG, GZMB, and GZMH." (PMID 37542039, 2023). "However, several cytotoxic enzymes and inflammatory cytokines, including GZMA, GZMB, GZMK, GNLY, and TNF were downregulated in TRM in achalasia, consistent with a previous study of TRM in MS42." (PMID 37542039, 2023).
adenoma (1 paper, 2020). A neoplasm arising from the epithelium. "Numbers of Granzyme B+ cells were not significantly changed in large tumors but accumulated in small adenomas of Stat1∆IECApcMin mice." (PMID 32444775, 2020).
alopecia (1 paper, 2023). Hair loss usually from the scalp. "The impact of GzmB on the decorin-TGF axis in scarring alopecia should be further explored." (PMID 36830757, 2023).
anaplastic large cell lymphoma (1 paper, 2025). Anaplastic large cell lymphoma (ALCL) is a rare and aggressive peripheral T-cell non-Hodgkin lymphoma, belonging to the group of CD30-positive lymphoproliferative disorders, which affects lymph nodes and extranodal sites. "Increased STAT3 activity, GZMB expression, and CD30 expression are markers of anaplastic large cell lymphomas (ALCL) of T cell origin, which PWH are of increased risk of developing." (PMID 40627772, 2025).
anemia (1 paper, 2023). A reduction in the number of red blood cells, the amount of hemoglobin, and/or the volume of packed red blood cells. "In support of this, here we show increased cytotoxic activity in response to gemcitabine chemotherapy, as demonstrated by an increase in Granzyme B. We also show that gemcitabine induces anemia in the form of reduced levels of hematocrit, hemoglobin and RBCs." (PMID 36646904, 2023).
Arthralgia (1 paper, 2023). "Higher levels of Tregs Perforin+Granzyme B+ cells were detected in Pool CoV-2- stimulated PBMC from volunteers who had arthralgia than in those who did not." (PMID 36969257, 2023).
Ascites (1 paper, 2023). Accumulation of fluid in the peritoneal cavity (between the layers of the peritoneum that lines the abdomen). "The most pronounced ascites-induced effects were the significant decreases in p85 and Granzyme B protein expressions, especially observed during T and NK cell activation." (PMID 37684704, 2023).
astrocytoma (1 paper, 2024). "OS analysis confirmed that the expression of GZMB was related to a poor survival in both astrocytoma and GBM, suggesting that mechanisms of survival are activated in PBTs that protect them from the activation of immune effectors." (PMID 38816839, 2024).
Atrophy (1 paper, 2023). Any weakening or degeneration, especially through lack of use. "A cytotoxic T cell is a granzyme B+CD8+CD3+ T cell, mainly secret granzyme B. Granzyme B is a serine protease that may mediate allograft injury and inflammatory interstitial fibrosis and tubular atrophy (i-IFTA)." (PMID 37374379, 2023). "Antioxidants, such as tocopherol and ascorbate, may neutralize the ROS and thus may delay granzyme-B-driven pathogenesis of inflammatory interstitial fibrosis and tubular atrophy." (PMID 37374379, 2023).
autoimmune encephalitis (1 paper, 2025). Inflammation of the brain secondary to an immune response triggered by the body itself. "In lesions of neuron‐targeted autoimmune encephalitis, CD8+ T cells expressed TRM markers such as Granzyme B, TOX, PD‐1, CD69, and BCL2." (PMID 41388658, 2025). "In mouse models of autoimmune encephalitis, PD‐1+ TRM produced IFN‐γ, TNF, Granzyme B, and perforin, and immunohistochemistry revealed a close interaction between TRM and neurons expressing self‐antigens, leading to neuronal loss and focal neuroinflammation." (PMID 41388658, 2025).
bacterial pneumonia (1 paper, 2022). Acute infection of the lung parenchyma caused by bacteria (e.g., Streptococcus pneumoniae, Haemophilus influenzae, Chlamydia pneumoniae, Mycoplasma pneumoniae, and Legionella pneumophila). "Third, we identified a protease activity sensor, BV01, that contributes to etiology stratification by detecting the activity of GZMB, which is expressed at higher levels in a mouse model of viral pneumonia than bacterial pneumonia." (PMID 35696579, 2022).
Brain atrophy (1 paper, 2017). Partial or complete wasting (loss) of brain tissue that was once present. "The CSF of patients with MS contains abundant granzyme B and IL-1β, and CSF IL-1β concentrations correlate with MS-associated brain atrophy." (PMID 28655310, 2017). "Though there is a published correlation between IL-1β in CSF and brain atrophy, no published studies have correlated granzyme B levels with clinical or radiographic measures of pathology in progressive forms of MS." (PMID 28655310, 2017).
brucellosis (1 paper, 2024). Brucellosis is a bacterial infection that spreads from animals to people via unpasteurized dairy products or by exposure to contaminated animal products or infected animals. "Multiple activation markers, such as CD69, MKI67, CCL5, CTLA4, IFNG and GZMB, were found to be enriched in the NK cells of brucellosis patients, indicating the presence of an activated NK cell response as a distinctive feature for brucellosis patients, especially for those at the acute stage." (PMID 39135683, 2024).
bullous pemphigoid (1 paper, 2018). Bullous pemphigoid (BP) is the most common form of autoimmune bullous dermatosis. "Following western blot and ATOMS analyses indicating that both α6 and β4 integrin sub-units, collagen VII and collagen XVII are substrates for GzmB, we sought to assess their integrity in bullous pemphigoid, dermatitis herpetiformis, and EBA skin samples." (PMID 29946113, 2018). "Similar to what observed in bullous pemphigoid and dermatitis herpetiformis, GzmB was found predominantly in neutrophils." (PMID 29946113, 2018). "As GzmB is elevated at the DEJ of bullous pemphigoid, dermatitis herpetiformis, and EBA, and capable of cleaving key junctional proteins, the direct impact of GzmB proteolysis on DEJ integrity in freshly-isolated human skin was assessed." (PMID 29946113, 2018). "Immunohistochemistry of patient skin samples from bullous pemphigoid, dermatitis herpetiformis, and EBA indicated that GzmB accumulated at the DEJ." (PMID 29946113, 2018). "We also demonstrated that in diseased human skin biopsies of bullous pemphigoid, dermatitis herpetiformis and EBA, sub-epidermal blisters display elevated levels of GzmB at the DEJ accompanied by degradation of the newly discovered GzmB substrates α6/β4 integrin, collagen VII, and collagen XVII." (PMID 29946113, 2018). "While mostly absent in normal skin, GzmB is present at the DEJ in the sub-epidermal blistering conditions bullous pemphigoid and dermatitis herpetiformis in agreement with previous studies, and we have shown for the first time accumulation of this protease at the DEJ in EBA." (PMID 29946113, 2018).
calcific aortic valve disease (1 paper, 2018). "Previous study unveiled a close relationship between the upregulation of GZMB and human calcific aortic valve disease, indicating an important role of GZMB in vascular calcification." (PMID 29445095, 2018).
cardiopulmonary disease (1 paper, 2020). "Our earlier studies reported that GzmB cleaves ECM in non-ocular systems, implicating extracellular GzmB activity in pathological chronic inflammation, delayed wound healing, skin injuries, and cardiopulmonary disease." (PMID 32318066, 2020). "Our earlier work showed that GzmB cleaves ECM in non-ocular systems, implicating extracellular GzmB activity in pathological chronic inflammation, delayed wound healing, skin injuries, and cardiopulmonary disease." (PMID 32318066, 2020).
cavernous hemangioma (1 paper, 2022). A hemangioma characterized by the presence of cavernous vascular spaces. "The high co-expression of CXCR4 and GZMB suggested that pDCs function for anti-tumour as CD8+T cells in cavernous hemangiomas." (PMID 35865633, 2022).
Chlamydia infection (1 paper, 2015). "Chlamydia infection is known to interfere with apoptosis signaling induced by various stimuli like staurosporine, etoposide, TNF-α, FAS antibody and granzyme B/perforin." (PMID 25906164, 2015).
chlamydial infection (1 paper, 2013). "Following both primary and secondary genital chlamydial infection, TNF-α−/− mice exhibited elevated granzyme B production, but similar IFN-γ and antibody responses." (PMID 23483844, 2013).
choroidal neovascularization (1 paper, 2025). An eye disorder described by the growth of new blood vessels that originate from the choroid through a break in the Bruch membrane into the sub–retinal pigment epithelium (sub-RPE) or subretinal space. "Granzyme B (GzmB) is a serine protease elevated in human eyes with nAMD and contributes to choroidal neovascularization (CNV)." (PMID 41310732, 2025).
chronic GVHD (1 paper, 2011). "Despite not evident in the univariate analysis, the multivariate analysis revealed the donor granzyme B G/G or AG genotype was associated with lower incidence of chronic GVHD (adjusted HR, 0.61; 95% CI, 0.37–0.99; P = 0.05)." (PMID 21886827, 2011).
chronic hepatitis (1 paper, 2021). An active inflammatory process affecting the liver for more than six months. "CD11b+ cells also showed prominent granzyme B expression, as reported in Kupffer cells in patients with chronic hepatitis." (PMID 33621209, 2021).
chronic lung disease (1 paper, 2015). According to the definitions of the American and British Thoracic Societies, including pulmonary functional tests, X-rays, and CT scans for items such as fibrosis, bronchiectasis, bullae, emphysema, nodular or lymphomatous abnormalities. "We have shown that these cells produce increased cytotoxic (granzyme b and perforin) and inflammatory (IFNγ and TNFα) mediators in several adult chronic lung diseases and hypothesised that similar changes would be evident in children with BE." (PMID 26258716, 2015).
chronic tonsillitis (1 paper, 2021). "Single-cell and spatial maps confirmed that CD68+ cells were correlated with the enhanced Granzyme B expression and CD3+ cells exhibited enrichment of CD4+ phenotype in chronic tonsillitis." (PMID 34045665, 2021).
colorectal adenocarcinoma (1 paper, 2019). The most common type of colorectal carcinoma. "This indicated that high concentration of IL-24 mainly influenced perforin/granzyme B pathway for cytolytic function of CD8+ T cells in colorectal adenocarcinoma." (PMID 31921658, 2019).
complication (1 paper, 2021). Any disease or disorder that occurs during the course of, or because of, another disease, treatment, or procedure. "Moreover, the presence of pulmonary complications was closely associated with an increase in the circulation of the proportion of short-living effector CD27–CD62L–CD8+ T cells, as well as mature T cells capable of producing perforin, granzyme B, and IFNγ." (PMID 34832564, 2021).
conjunctival melanoma (1 paper, 2021). "For this purpose, we analyzed Ki-67 as a proliferation marker, CD68 as an myeloid cell marker, α-SMA as a marker for perivascular cells, myofibroblasts and smooth muscle cells and granzyme B, which is expressed in cytotoxic T cells in the healthy conjunctiva and in conjunctival melanoma." (PMID 34544377, 2021).
coronary atherosclerosis (1 paper, 2022). Atherosclerosis of the coronary vasculature. "Hence, GZMB may function as an essential mediator to connect RA and the emergence of coronary atherosclerosis in the subgroup of RA patients." (PMID 36072953, 2022).
cutaneous vasculitis (1 paper, 2021). Inflammation of the blood vessel wall characterized by palpable purpura. "Additionally, there was a markedly higher percentage of Granzyme B+ T-cells in the Ki67+ T-cell populations derived from the skin of patients with cutaneous vasculitis compared with HDs." (PMID 34625602, 2021).
DRESS syndrome (1 paper, 2022). "Immunophenotypical features identify DRESS syndrome: cutaneous effector lymphocytes represent a large quantity of the polyclonal CD8+ granzyme B+ T lymphocytes." (PMID 36059007, 2022).
E. coli infection (1 paper, 2017). "For this purpose, we used a murine model of E. coli abdominal infection in WT mice and mice deficient in gzmA and/or gzmB." (PMID 28694562, 2017). "The present study is the first, to our knowledge, showing the pattern of intracellular expression of gzmA and gzmB by different lymphocyte populations before and after induction of E. coli infection." (PMID 28694562, 2017). "Curiously, in blood, the percentage of NK cells expressing gzmA and gzmB increased after E. coli infection, suggestive of differential responses at the primary site of infection and systemically." (PMID 28694562, 2017).
encephalitis (1 paper, 2017). An acute inflammatory process affecting the brain parenchyma. "These Th17 cells may then produce multiple mediators, including cytolytic enzymes, such as granzyme B, strongly favoring the development of encephalitis." (PMID 28139719, 2017).
endometrial tumors (1 paper, 2021). "To understand the underlying mechanisms involved in the suppression of CD8+ T cell cytotoxic killing in endometrial tumors, we investigated whether there were changes in the expression of granzyme A (GZA), granzyme B (GZB), perforin (PRF), and PD-1 in CD103+ and CD103-CD8+ T cells." (PMID 33968059, 2021).
endotoxemia (1 paper, 2020). "Increased levels of GzmA and GzmB have been found in patients with severe gram negative bacterial infections as well as in healthy volunteers with an experimental endotoxemia with lipopolysaccharide (LPS)." (PMID 32655547, 2020).
enteropathy (1 paper, 2023). "Similar to protein expression, especially NV+ tissues showed a highly induced expression of GzmB within both enteropathy groups, possibly resulting from the increased activation of NV-specific TRM cells in the infected tissues." (PMID 36282455, 2023). "At the transcriptional level, expression discriminated already tissues of patients without visual inflammation (Marsh 0) from HC tissues, suggesting GZMB as a potential biomarker for active enteropathy without histological signs of inflammation." (PMID 36282455, 2023).
eosinophilia (1 paper, 2019). "Strong granzyme B+, interferon (IFN)-γ+ CD8+ cytotoxic T cell and circulating regulatory T (Treg) cell responses were noted during allograft rejection, along with significant eosinophilia and elevated serum IL-5 and eotaxin levels." (PMID 31624262, 2019).
epidermolysis bullosa (1 paper, 2020). Epidermolysis bullosa (EB) is a group of genetic skin diseases that cause the skin to blister very easily. "Among these is granzyme B, which is highly active in human epidermolysis bullosa." (PMID 32497513, 2020).
Erythema (1 paper, 2025). Redness of the skin, caused by hyperemia of the capillaries in the lower layers of the skin. "On the other hand, in EM, infection or drug exposure leads to the excessive expression of inflammatory mediators, such as interferon-gamma (IFN-γ), tumor necrosis factor-alpha (TNF-α), perforin, and granzyme B, resulting in severe skin inflammation, erythema, and epidermal destruction." (PMID 40104458, 2025).
falciparum malaria (1 paper, 2018). "Patients with falciparum malaria also had signs of T-cell subset activation (i.e. increased granzyme B and CX3CL1) and T-cell exhaustion as assessed by high levels of TIM-3 particularly in patients co-infected with HIV." (PMID 30563486, 2018). "In order to further characterize the T-cell response during falciparum malaria we measured granzyme B as a marker of activated CD8+ T-cells and TIM-3 that could promote induction of effector memory T-cells." (PMID 30563486, 2018).
fibrosarcoma (1 paper, 2025). A malignant mesenchymal fibroblastic neoplasm affecting the soft tissue and bone. "For example, a preclinical study found pretreatment with trabectedin improved the response to anti–PD-1 in a murine model of fibrosarcoma and led to upregulation of CD8, GZMB, PRF1, and CXCL10 mRNA expression in trabectedin-treated tumors." (PMID 39777457, 2025).
gallbladder carcinoma (1 paper, 2025). "Immunofluorescence staining of gallbladder carcinoma tissue reveals that CD4 cells highly express the Treg cell marker, while CD8 cells show high expression of the inhibitory molecule PD-1 and the cytotoxic molecule GZMB." (PMID 41487509, 2025).
genital wart (1 paper, 2025). "The increased expression of GZMB, IFNG, IL-12B, and IL-8 and the decreased expression of NFATC4 and IL-7 in genital wart samples were highlighted." (PMID 40142865, 2025).
geographic atrophy (1 paper, 2020). "Next, we assessed the distribution of GzmB+ choroidal cells in donor eyes with geographic atrophy (GA from AMD), eyes with the exudative (wet) form of AMD and eyes with soft drusen (SD, an early precursor to AMD pathology)." (PMID 32318066, 2020).
glomerulonephritis (1 paper, 2025). A renal disorder characterized by damage in the glomeruli. "In mice, blocking IFN-I signaling reduces IRF7 and granzyme B expression in T cells, thus ameliorating glomerulonephritis." (PMID 40393992, 2025).
Guillain-Barre syndrome (1 paper, 2020). A spectrum of rare post-infectious neuropathies that usually occur in otherwise healthy patients. "In clinical neuropathies, granzymes have been labeled in the peripheral nerves, and granzyme B positive lymphocytes are seen in close apposition to neurons in the DRG in the late-stages of Guillain-Barré syndrome (GBS) in which axon degeneration is observed." (PMID 32153361, 2020).
H1N1 virus infection (1 paper, 2023). "Meanwhile, compared to the H1N1 virus infection group, we also found that H1N1 virus-infected mice with RosA treatment had lower levels of CD8+ (green) T cells and the expression of cytotoxic effectors Granzyme B (pink) and TNF-α (red) in the lung tissues." (PMID 37891648, 2023).
hematoma (1 paper, 2025). A hematoma is a collection of blood from a vascular structure into an extravascular space. "We found that the CD8_GNLY subcluster was increased in the peripheral blood and hematoma of ICH patients, along with high expression of effector genes such as GNLY, GZMB and GZMH." (PMID 41238793, 2025).
hemorrhage (1 paper, 2013). Loss of blood from the vascular compartment to the exterior or into nonvascular body space as a result of rupture or severance of the blood vessels. "The correlation between the number of brain petechial hemorrhages and poor clinical outcomes has led to the proposal that blood-brain barrier disruption may be partially due to vascular endothelial apoptosis caused by granzyme B and perforin-mediated cytotoxicity." (PMID 23630573, 2013).
herpesvirus infection (1 paper, 2015). "PRF1 interacts with GZMB in cytotoxic cell death, and plasma granzyme expression is elevated in herpesvirus infection, so the link between GZMB polymorphisms and EBV-positive HLH has been investigated." (PMID 25430668, 2015).